GLI1 (GLI family zinc finger 1)
Diseases named in the same sentence as GLI1 in open-access papers (continued):
Sharing a sentence is not in itself a finding about the gene and the disease.
cancer (continued). "Moreover, the GLUT1 (glucose transporter) and MCT4 (lactate transporter), which are usually highly expressed primarily in cancer cells, were downregulated by GLI1 knockdown." (PMID 36046646, 2022). "In previous data, GLI1 mediated HH pathway can induce apoptosis in various cancer cells." (PMID 36046646, 2022). "Shh/Gli1 signaling is activated on tumorigenicity of cancer cells." (PMID 35802536, 2022). "It is noteworthy that although the involvement of GLI1 and HH pathway in HSC-3 is also supported by our previous study using GANT-61 inhibitor, additional GLI1 gene editing studies could constitute the proof-of-concept of its role in the cancer context." (PMID 36552049, 2022). "Moreover, pimavanserin also impaired the expression of several Gli1 downstream cancer stem cell markers, including Oct-4, SOX2 and NANOG, and suppressed the size and number of PANC1 tumorspheres." (PMID 34439102, 2021). "Similarly, TGF-β1 can also induce Hh-GLI1 signaling to promote EMT phenotype and promote migration and metastatic characteristics in mesenchymal A549 LAC cells, which further supports the role of GLI in mediating TGF-β1-driven EMT in cancer." (PMID 34572373, 2021). "HH pathway upregulation of GLI1 enhances the CXCL12 induced migration of cancer cells." (PMID 33494284, 2021). "As GLI1 is most amenable to activation by both SMO-dependent and SMO-independent axes among the Hh pathway components, it is unsurprising that its expression is more commonly associated with poor prognosis in Hh-active cancer patients." (PMID 34572373, 2021). "Gli1 is one of the most advanced hedgehog (Hh) signal molecules, which directly regulate the induction of various Hh target genes and are related to development and tissue regeneration, but also to unexpected effects such as cancer or neurodegeneration." (PMID 34801048, 2021). "Interestingly, FGFR1 and GLI1 also activate many downstream oncogenic genes, which lead to cancer cell migration, proliferation, and survival." (PMID 34722544, 2021). "Thus, the expression of SHH and GLI1 increased with the adenocarcinoma stages of cancer, suggesting a role of the Hh pathway in PCa proliferation." (PMID 32867229, 2020). "As EMT is crucial for cancer cell migration and invasion, in order to elucidate the role of the Shh/Gli1 pathway in the regulation of EMT in GC, the association between E-cad, VIM and Gli1 expression was investigated by immunohistochemistry in GC tissues." (PMID 32328197, 2020). "A variety of members of the Hh pathway have been found to be affected by mutations in human cancers, such as the inactivating mutations of Patch1 or SUFU or the activating alterations of SMO, Gli1, and Gli2, which lead to signaling pathway activation independently of ligand binding." (PMID 32984007, 2020). "We speculate that jointly targeting Gli1 and other cancer stemness biomarkers will provide a novel vision to treat GA." (PMID 32430068, 2020). "Abnormal expression of GLI1 affects the progression of cancer cells." (PMID 32986358, 2020). "Furthermore, double-staining results proved that CD105 expression (blood vessels) was around Gli1 expression (cancer cells)." (PMID 32430068, 2020). "Targeting GLI1 with Gant61 has been studied in other types of cancers, showing beneficial effects." (PMID 33396427, 2020). "Therefore, several components of the HH pathway are under investigation for targeted cancer therapy, particularly GLI1 and SMO." (PMID 32957513, 2020). "These indicated that GLI1 as a key transcription factor in the Hedgehog signalling pathway may play a crucial role in the chemotherapy-induced regulation of cancer stem cell-like properties." (PMID 32242101, 2020). "In conclusion, Gli1 may be a poor prognostic indicator and a potential cancer stemness-related protein in GA." (PMID 32430068, 2020). "Colocalization of Gli1 with cancer stemness-related proteins in GA tissue indicates that Gli1 may be an important stemness-related protein in GA." (PMID 32430068, 2020).
cancer (continued). "GLI1 was enriched in pathways in cancer that was the most significant pathway." (PMID 32242101, 2020). "Furthermore, the mRNA analysis of paired normal and cancer tissues from patients suggested that GLI1 and stemness were positively correlated and coupled with adverse effects on differentiation-promoting factors." (PMID 32814764, 2020). "Her2 overexpression is associated with an increased subpopulation of cancer stem cells and correlates with activation of the PI3K/AKT pathway, leading to increased expression of stem cell markers Oct3/4, Notch1, Notch2, Jagged1 and Gli1." (PMID 31608299, 2019). "Interestingly, Gli1 seems to play a more prominent role in cancer than Gli2 or Gli3, at least based on the number of published studies." (PMID 30754706, 2019). "Therefore, elucidation of the activation mechanism of GLI1 by HH signals is also important to understand the mechanism of HH-GLI1-mediated cancer development." (PMID 30675521, 2019). "Next, we sought to investigate whether this GLI1 regulation by PI3Kα/mTOR is also evident in other HH-driven paediatric cancers." (PMID 31492956, 2019). "Moreover, protein expression of GLI1 was enhanced by MEP50/PRMT5 and expression of MEP50, PRMT5, and GLI1 target genes was upregulated in HH-expressing cancers." (PMID 30675521, 2019). "Furthermore, attenuation of GLI1-associated DDR by IL-24 increased caspase-3 and PARP activity, resulting in cancer cell apoptosis." (PMID 31783569, 2019). "However, the role of the HH-GLI1 pathway in cancer and the activation mechanism of GLI1 in HH signalling after dissociation from SUFU are not fully understood." (PMID 30675521, 2019). "Activation of GLI1 might be involved in increased cancer cell resistance to doxorubicin, paclitaxel, and cisplatin by upregulation of the multidrug resistance protein-1 (MDR-1)." (PMID 31027259, 2019). "However, the role of the HH-GLI1 pathway in cancer and the activation mechanism of GLI1 in HH signalling after dissociation from its inhibitor, SUFU, are not fully understood." (PMID 30675521, 2019). "In addition, Rab1a was correlated to S6K in 7 cancers, Gli1 in 2 cancers, AKT in 7 cancers, HER2 in 2 cancers, and EGFR in 6 cancers." (PMID 31527621, 2019). "In fact, Gli-1 is involved in several cellular functions such as cell proliferation, survival, and migration, as well as cancer cell stemness and self-renewal, and its overexpression correlates with malignancy of several cancers including GBM." (PMID 30978987, 2019). "GLI1 has been shown to regulate cancer stem cells in various malignancies." (PMID 31394751, 2019). "The GRIK2 Q/R, Y/C, and GABRA3 I/M sites emerged as sites with a remarkable editing decrease in GBM (with an editing drop ranging from − 82 to − 74% Δ medians) followed by GLI1 R/G site (− 27% Δ medians), the latter playing a key role in modulating the Hedgehog (HH) signaling in cancer." (PMID 30760294, 2019). "Hence, the most efficacy strategy to block Hh signaling in cancer appears to be the pharmacological inhibition of the final and most powerful effector Gli1." (PMID 31601026, 2019). "The reduction of GLI1 protein in the nucleus after dual PI3Kα and mTOR inhibition indicates a requirement for PI3Kα and mTOR activities to sustain nuclear GLI1 in HH-driven cancers." (PMID 31492956, 2019). "Our present results suggest that MEP50/PRMT5 might function in cancer cell proliferation and invasion at least in part via activation of GLI1." (PMID 30675521, 2019). "Thus, penfluridol suppresses the proliferation and growth of GBM cancer cells is based on inhibiting Akt-mediated phosphorylation of GLI1." (PMID 31614431, 2019). "Transforming growth factor-beta (TGF-β) has also been demonstrated to upregulate GLI1 and GLI2 via the SMAD3 pathway and may also lead to GLI protein accumulation in cancer cells." (PMID 30759860, 2019). "As a novel target, Gli1 worth further study, especially in Her2-targeted therapy-resistant cancers." (PMID 29321573, 2018).
cancer (continued). "Elucidating the molecular mechanism of the regulation of GLI1 is critical for understanding Hh signal transduction, normal embryonic patterning, and pathological conditions such as human congenital anomalies and cancers arising from dysregulated Hh signaling." (PMID 29662197, 2018). "Further suppression of intracellular Gli-1 expression might be involved in the action of mGluR4 on cancer cells." (PMID 29867331, 2018). "Moreover, it is well documented that Gli-1 mediates the mitogen effects of the SHH pathway in the regulation of growth of proliferating normal cells as well as several cancer cells." (PMID 29867331, 2018). "However, Gli-1 is highly expressed in diverse cancer cells and critically involved in the tumorigenesis and cancer growth, including GBM." (PMID 29867331, 2018). "Second, we also detected side population of cancer cells after GLI1 alteration." (PMID 28404967, 2017). "Moreover, previous studies have shown that these stem-like cancer cells harbor aberrantly activated HH/Gli1 signaling pathway." (PMID 29225516, 2017). "Hedgehog signaling related regulator GLI1 is known to be vital in cancer biology." (PMID 28413604, 2017). "From a therapeutic point of view, the fluctuating kinetics of GLI1 levels following a DYRK1B inhibition are problematic as suboptimal or short-term treatments with DYRK1B antagonists might result in concomitant upregulation of oncogenic GLI1 in cancer cells." (PMID 27903983, 2017). "In particular, understanding the mechanisms balancing GLI1 stability versus degradation may have therapeutic value for cancers in which GLI1 is overexpressed." (PMID 28562331, 2017). "We have data to show that knocking down GLI1 or GLI2 will sensitize cancer cells to 5-FU treatment." (PMID 28413604, 2017). "Now, GLI1 has been found to be overexpressed in many kinds of cancers include ESCC." (PMID 29190924, 2017). "GANT61, a promising GLI1 inhibitor, appears to be highly effective against human malignant cells and in xenograft mouse models by targeting almost all of the classical hallmarks of cancer." (PMID 27275540, 2017). "Down-regulation of GLI1 or GLI2 sensitized cancer cells to 5-FU treatment." (PMID 28413604, 2017). "Furthermore, we also showed that PTTG1 promoted EMT and cancer metastasis in ESCC cell lines at least via the activation of GLI1." (PMID 29190924, 2017). "We further demonstrated and SMO antagonist BMS833923 was not able to sensitize cancer cells to 5-FU (data not shown here), suggesting that up-regulation of GLI1 was not caused by canonical Hh signaling." (PMID 28413604, 2017). "Additionally, GLI-1 gene transcription factors have been functionally related to cancer stem cell self-renewal capacity and tumorigenicity in solid glioma tumors." (PMID 28978016, 2017). "These oncogenic properties together with the capacity of GLI1 to integrate and relay common SMO-independent cancer-promoting cues such as receptor-tyrosine kinase pathways, PI3K and MAP kinase signaling render GLI1 an attractive molecular target for cancer therapy." (PMID 26784250, 2016). "Interestingly, activation of GLI1 reinduced, at least in part, cancer cells to invade and migrate in the presence of metformin or MEK-I alone and in combination." (PMID 26673006, 2016). "Therefore, several components of the Shh pathway (Shh, SMO, and GLI1/2) are viable therapeutic targets for anti-cancer therapies." (PMID 26891329, 2016). "Therefore we performed this meta-analysis aiming to discover the correlation between Gli1 positivity and clinical prognosis in patients suffering from diverse carcinomas." (PMID 26899488, 2016). "The mechanisms of this regulation have not been thoroughly analyzed and further study could be important for understanding how GLI1 contributes to cancer development and may identify potential therapeutic targets." (PMID 26633513, 2015).
cancer (continued). "Furthermore, PCAF was found to ubiquitinate GLI1 in response to DNA damaging agents leading to its degradation, thereby preventing the growth and survival promoting activity of GLI1 overexpressing cancer cells." (PMID 26633513, 2015). "Downregulation of GLI1, or HIF2a, or both sensitizes cancer cells to radiation." (PMID 26633513, 2015). "Limited Gli-3 mutations are limited and not reported in cancer samples and over expression of Gli-1 is associated with poor prognosis." (PMID 26389956, 2015). "Indeed, GLI1 was revealed to up-regulate the expression of a variety of genes crucial for many cancer cell properties." (PMID 26318045, 2015). "In addition to promoting tumors, GLI1 also has a prominent role in inducing chemo-/radio-resistance of cancer cells through the regulation of multiple mechanisms." (PMID 26633513, 2015). "Finally, it has been described a correlation between GLI1 expression levels and/or prognosis and recurrence in some cancer types." (PMID 26258070, 2015). "Gli1, a member of the Gli family, was originally identified as an amplified gene in malignant glioma and was proven to be able to regulate stem cells and cancer stem cells." (PMID 24889938, 2014). "In conclusion, As2O3 may induce HCC CSC differentiation, inhibit cancer recurrence after radical resection, and prolong survival as a result of down-regulation of GLI1 expression." (PMID 24678763, 2014). "Both CK2α and Gli1 genes are over-expressed in a variety of cancers." (PMID 25422081, 2014). "Besides, Gli1 has been considered a suitable target for cancer therapy because it is downstream of several signaling pathways." (PMID 23555905, 2013). "All eight cancers with Gli-1-positive nuclei expressed BMI1." (PMID 23046527, 2012). "Aberrant activation of GLI1 expression might arise from a number of possible mechanisms with both canonical Hh-pathway-dependent and non-canonical Hh-independent activation of GLI1 reported for different cancers." (PMID 21505458, 2011). "In addition to normal development, the Shh-GLI1 pathway is critically involved in tumorigenesis, cancer growth and cancer stem cell self-renewal." (PMID 21119888, 2010). "GLI1 gene amplification was extensively studied in other types of human cancers." (PMID 21119888, 2010). "Although all three Gli proteins are implicated in stem cell biology, development and disease pathogenesis, evidence suggestive of crosstalk with MAPK signaling is especially enticing for Gli1, particularly in relation to a role in tumorigenesis and cancer progression." (PMID 20865152, 2010). "GLI1, in particular, plays a significant role in human cancers." (PMID 21119888, 2010). "As expected, all Gli-1 nuclear-positive cancers in the current study expressed CXCR4, COX-2, and VEGF, which was indicative of a cancer progenitor cell-like surface characteristic that might contribute to cancer relapse and treatment failure." (PMID 18475300, 2008). "In addition, cancer cells expressing Gli1 under the CMV promoter are resistant to cyclopamine-mediated apoptosis." (PMID 15482598, 2004). "Indeed, in our study, GLI1 was highly overexpressed in BCC cancer stem cells compared to healthy margin cells, and its expression was reduced following the treatment with both essential oils, although only T. serpyllum showed a statistically significant decrease." (PMID 40868944, 2025). "Hypoxia inducible factor-1 (HIF-1) promotes cancer stemness and invasive behavior of CCC by modulating Shh, Smo and Gli1.279,280 HH signaling pathway protein might promote the interaction between cancer cell and stromal cell and eventually further promotes cancer progression." (PMID 37596267, 2023). "Some of the mentioned results are contrary to ours, since we clearly found a possible GLI1 protective role in KIRC, based on the Cox test where samples with downregulated GLI1 immunoreactivity were associated with earlier death in the course of this cancer type." (PMID 37964226, 2023).
cancer (continued). "However, the underlying molecular mechanisms in cancer cells and nerves within Gli1-derived PNR have not previously been comprehensively analyzed." (PMID 38041128, 2023). "Although GLI-1 is not highly expressed in differentiated tissues, abnormal activation of the protein has been linked to the promotion of several hallmarks of cancer, including proliferation, angiogenesis, metastasis, survival, metabolic renewal, and resistance to chemotherapy." (PMID 37304485, 2023). "Thus, inhibiting GLI1-mediated transcription seems to be an alternative strategy for successful cancer therapy, making it necessary to explore the unknown role of GLI1 in cancer." (PMID 36046646, 2022). "Additionally, GC patients with high GLI1/GLI2 and ABCG2 signatures were associated with a shorter overall survival (OS) and higher cancer relapse, suggesting that higher expressions of these genes predicted a poorer outcome in GC patients who underwent 5-FU and cisplatin-based chemotherapy." (PMID 34638233, 2021). "Whether overexpressed due to canonical, non-canonical, or genetic mutation, elevated GLI1 expression drives several of the hallmarks of cancer including DNA damage repair, cell proliferation, and metastasis." (PMID 34113570, 2021). "GLI1, a transcription factor of HH pathway, is believed to regulate the expression of genes involved in proliferation, survival, and cell viability and the blockage of HH pathway may inhibit these cancer hallmarks." (PMID 33312948, 2020). "However, the role of PI3K-AKT-mTOR in regulating GLI1 in cancer appears to be context dependent." (PMID 31244888, 2019). "It has been shown that Gli1 inhibition could promote apoptosis in other cancer cells." (PMID 31455353, 2019). "An alternative, intriguing hypothesis points to the existence of noncanonical, compensatory signal pathways that drive SMO-independent GLI1 activation in cancer, thus bypassing the inhibitory activity of SMO antagonists and hence contributing to the acquisition of resistance." (PMID 30558232, 2018). "In addition, previous reports pointed out that Gli1 knockdown could suppress cancer cell growth, invasion, colony formation and induce cell cycle arrest, which further validates Gli1 as an oncogene." (PMID 29375376, 2017). "This indicates that GLI1 could serve as a prognosis and diagnosis marker for cancer patients." (PMID 28562331, 2017). "Finally, we determined whether Arf6 similarly regulates Hh signalling in human cancer lines by examining changes in Gli1 expression levels following Arf6 RNAi knockdown." (PMID 28281543, 2017). "Because there are no GLI1 antibodies suitable for immunohistochemistry in paraffin-embedded tissues, we took the advantage of the CTGA data to test whether higher GLI1 transcript level is correlated with cancer relapse or patient survival in those patients who underwent chemotherapy." (PMID 28404967, 2017). "Thus, NQC induced apoptosis in cancers through inhibition of HH-GLI cascade by GLI1." (PMID 26846872, 2016). "Thus, inhibition of GLI1 blocks the replication-associated checkpoints and therefore, cancer cells with high proliferation rate and without proper cell cycle arrest/regulation will undergo cell death." (PMID 26633513, 2015). "Thus, understanding the largely unknown mechanisms of Gli1 activation will provide insights into the mechanism of cancer growth and will guide development of treatments." (PMID 26619401, 2015). "Thus, Gli1, which promotes the expansion of cancer stem cells, may be a potential therapeutic target for novel treatments for ER-positive breast cancer." (PMID 24889938, 2014). "If Gli1 and Gli2 can have additive effects, the specific expression and function of each one may depend on the tumoral context and in the signaling occurring in cancer cells." (PMID 23667589, 2013).